H2AC17 (H2A clustered histone 17)
Description:
Core component of nucleosome. Nucleosomes wrap and compact DNA into chromatin, limiting DNA accessibility to the cellular machineries which require DNA as a template. Histones thereby play a central role in transcription regulation, DNA repair, DNA replication and chromosomal stability. DNA accessibility is regulated via a complex set of post-translational modifications of histones, also called histone code, and nucleosome remodeling.
Synonyms: H2A.1; H2AFN; HIST1H2AM; H2A/n; dJ193B12.1
Gene: Protein-coding gene on chromosome 6 (27,892,699 to 27,893,185, reverse strand). Ensembl gene ENSG00000278677.
Subcellular location: Nucleus; Chromosome
Subcellular location (Human Protein Atlas): Nucleoplasm
Pathways (Reactome):
Chromatin organization: HATs acetylate histones; HDACs deacetylate histones; RMTs methylate histone arginines
Disease: Dengue Virus-Host Interactions; HCMV Early Events; HCMV Late Events
Metabolism of proteins: Metalloprotease DUBs; UCH proteinases; Ub-specific processing proteases
Gene Ontology:
Molecular function: enzyme binding; protein binding; structural constituent of chromatin; DNA binding; protein heterodimerization activity
Biological process: chromatin organization; heterochromatin formation
Cellular component: extracellular exosome; nucleoplasm; nucleosome; nucleus; chromosome
Genetic constraint (gnomAD): Loss-of-function variants: 10 observed, 6.9 expected, observed/expected ratio (o/e) 1.45, 90% interval 0.86 to 1.92. That is too few expected variants to judge how well the gene tolerates losing a copy. Missense variants: 207 observed, 186.38 expected, observed/expected ratio (o/e) 1.11, 90% interval 0.99 to 1.25. Synonymous variants: 138 observed, 80.84 expected, observed/expected ratio (o/e) 1.71, 90% interval 1.48 to 1.93.
Homologues: Orthologues: Drosophila melanogaster His2A:CG31618 (85% identical), Drosophila melanogaster His2A:CG33808 (85% identical), Drosophila melanogaster His2A:CG33814 (85% identical), Drosophila melanogaster His2A:CG33817 (85% identical), Drosophila melanogaster His2A:CG33820 (85% identical), Drosophila melanogaster His2A:CG33823 (85% identical), Drosophila melanogaster His2A:CG33826 (85% identical), Drosophila melanogaster His2A:CG33829 (85% identical), Drosophila melanogaster His2A:CG33832 (85% identical), Drosophila melanogaster His2A:CG33835 (85% identical), Drosophila melanogaster His2A:CG33838 (85% identical), Drosophila melanogaster His2A:CG33841 (85% identical), and 8 more. Paralogues in human: H2AC11 (100% identical), H2AC13 (100% identical), H2AC15 (100% identical), H2AC16 (100% identical), H2AC7 (99% identical), H2AC12 (98% identical), H2AC18 (98% identical), H2AC19 (98% identical), H2AC4 (98% identical), H2AC6 (98% identical), H2AC8 (98% identical), H2AC14 (98% identical), and 15 more.
Diseases named in the same sentence as H2AC17 in open-access papers:
H2AC17 is named in the same sentence as 2 diseases in open-access papers, as found by Europe PMC text mining. Sharing a sentence is not in itself a finding about the gene and the disease. The quoted sentences say what the papers report.
infection (1 paper, 2023). The state of being infected such as from the introduction of a foreign agent such as serum, vaccine, antigenic substance or organism. "The results indicate that the combination of ADIPOR1, CENPO, E2F2, and H2AC17 genes has the potential as characteristic genes for diagnosing and studying the acute phase of SFTS virus (SFTSV) infection." (PMID 37896902, 2023).
H2AC17 also shares sentences with these, for which no sentence is quoted: systemic lupus erythematosus (1 paper).